SPP1 (secreted phosphoprotein 1)
Diseases named in the same sentence as SPP1 in open-access papers (continued):
Sharing a sentence is not in itself a finding about the gene and the disease.
prostate carcinoma (continued). "We chose to analyze single-cell sequencing data from three tumors where SPP1 expression was positively correlated with immune infiltration including Thyroid carcinoma (THCA), Colon adenocarcinoma (COAD), and prostate cancer (PRAD), respectively." (PMID 38648200, 2024). "OPN/SPP1, recognized as a chemokine-like sialic acid-rich glycoprotein, has been reported to be overexpressed in various malignancies, including prostate cancer." (PMID 38167126, 2024). "In advanced and castration resistant prostate cancer, spatial transcriptomics and imaging mass spectrometry flow cytometry showed co localization of TREM2 +/SPP1 + TAM with hypoxic and lipid rich tumor regions, adjacent blood vessels, and specific CAF subgroups." (PMID 41488638, 2025). "Hence, our data revealed Spp1 as another macrophage cytokine/growth factor and its mediated mechanism to upregulate PIN cell growth, thus promoting prostate cancer development." (PMID 35457063, 2022). "OPN (or secreted phosphoprotein-1) acts via binding to αvβ3 integrin and CD44 and plays a key role in both the metastatic spread as well as the drug-sensitivity of breast and prostate cancer." (PMID 32751181, 2020). "The combination of PTEN/SMAD4 does not predict risk for prostate cancer recurrence, but the PTEN/SMAD4/CCND1/SPP1 four-gene signature does." (PMID 31551414, 2019). "Our study confirms that upregulation of SPP1 is a feature intrinsic to androgen-resistant metastatic prostate cancer, independent of the site of metastasis." (PMID 17430594, 2007). "Upregulation of SPP1 and downregulation of CHRDL1 and CNN1 (genes involved in bone biology) in metastasis from all sites analyzed are found which suggests they are changed early on and could belong to the genes that make prostate cancer metastatic cells bone-gravitating." (PMID 34209195, 2021).
atherosclerosis (107 papers, 2010 to 2026). A disease characterized by the build-up of fatty material and calcium deposition in the arterial wall resulting in partial or complete occlusion of the arterial lumen. "It has been reported that Spp1-deficient leukocytes provide substantial protection against Ang II-accelerated atherosclerosis and AAA formation." (PMID 40440080, 2025). "Secreted phosphoprotein 1 (SPP1, osteopontin, which has been implicated as an important factor in remodeling processes) is increased in atherosclerosis." (PMID 38469142, 2024). "Osteopontin (OPN, encoded by Spp1), a secreted proinflammatory protein involved in the proliferation of VSMCs, is an important driver of atherosclerosis." (PMID 36034838, 2022). "Additionally, proinflammatory CD4+ CD28null T cells and dysfunctional TREM2- SPP1+ foamy macrophages, which were associated with atherosclerosis progression and poor prognosis, were expected to be potential therapeutic targets for future precision medicine." (PMID 36855107, 2023). "We observed that due to the high expression of genes involved in lipid metabolism, although in minority, our macrophage subtype (SPP1+ macrophage) may be associated with atherosclerosis." (PMID 37706320, 2023). "According to previous studies, a number of inflammatory and autoimmune conditions, such as Crohn’s disease, cirrhosis, obesity, atherosclerosis, cancer, multiple sclerosis (MS), RA, and osteoarthritis (OA), have elevated SPP1 concentrations." (PMID 41384115, 2025). "SPP1 itself serves as a key gene marker for lipid‐related conditions, with SPP1+ macrophages identified across diverse pathological settings, including adipose tissue dysfunction, liver disease, atherosclerosis, intestinal disorders, and cancer." (PMID 40395129, 2025). "We identified several genes, including Cemip, Lum, Mfge8, Spp1, and Serpina3, which are known to be involved in atherosclerosis-induced gene expression." (PMID 38289873, 2024). "Overexpression of Spp1 leads to vascular inflammation, endothelial cell proliferation and migration, and ultimately promotes atherosclerosis as well as exacerbates vascular fibrosis and remodeling." (PMID 38689862, 2024). "Obesity and high blood glucose through elevated SPP1 can induce insulin resistance, atherosclerosis, and diabetes." (PMID 38809924, 2024). "In addition, the presence of SPP1+ foamy macrophage signalling and the abundance of these cell subsets are significantly associated with the symptoms of disease progression in patients with atherosclerosis, including plaque rupturing, bleeding, and the recurrence of ischemic events after surgery." (PMID 36855107, 2023). "We further explored the differential cell-cell communication pathways between NC and atherosclerosis and found PVAT in atherosclerosis showed unique pathways related to fibrosis, like SPP1,63VCAM,64 and POSTN65." (PMID 37706320, 2023). "The mRNA level of SPP1 in coronary PVAT was significantly increased in atherosclerosis compared with NC in both single-cell and bulk level." (PMID 37706320, 2023). "A prominent example of such a common gene is SPP1, required for macrophage chemotaxis, critical in lipid peroxidation, and a pathological landmark of atherosclerosis." (PMID 35488341, 2022). "Based on the results, we concluded that XIST regulates the progression of atherosclerosis through the miR-539-5p/SPP1 axis." (PMID 35028010, 2022). "In atherosclerosis model mice, knockdown of SPP1 not only reduced atherosclerotic lesion size but also decreased the number of macrophages in the plaque." (PMID 33224526, 2020). "LASSO regression and SVM-REF also verified the pivotal role of SPP1 in atherosclerosis." (PMID 41293726, 2025). "Taken together, these results identify plausible candidate TFs that drove the phenotypic differences in SPP1+ foamy macrophages and indicate that the presence of CSF1+ mast cells may drive the phenotype of SPP1+ foamy macrophages in atherosclerosis." (PMID 36855107, 2023).
atherosclerosis (continued). "Furthermore, MuSiC and Scaden, based on different deconvolution principles, also showed consistent results, further validating the important role of SPP1+ foamy macrophages in poor prognosis in atherosclerosis." (PMID 36855107, 2023). "Our observation of Spp1 overexpression in ApoE−/− mouse model indicates that Spp1 may accelerate the process of atherosclerosis by inducing inflammation." (PMID 31446617, 2019). "Numerous studies suggest that SPP1 may contribute to the development and progression of cardiovascular diseases, including atherosclerosis, abdominal aortic aneurysm, dilated cardiomyopathy with heart failure, thoracic aortic dissection, and myocardial infarction, via the EMT pathway." (PMID 41293726, 2025). "Interestingly, Trem2+ LAMs expressing Spp1 showed a transcriptional profile similar to osteoclasts during advanced stages of murine atherosclerosis, and human multinucleated giant cells express MAM markers such as SPP1, MMP9, CHI3L1 in granulomatous slack skin." (PMID 37706477, 2023). "It was suggested that C0 C1QC+ macrophages, C1 SPP1+ macrophages, and C2 FCN1+ macrophages may play an important role in the progression of atherosclerosis." (PMID 39726810, 2024). "Taken together, these findings reveal that the unique and dysfunctional SPP1+ TREM2− type of foamy cells played an important role in atherosclerosis progression, which has not been elucidated in previous single-cell studies." (PMID 36855107, 2023). "Upregulated genes in BBA-derived VSMCs are related to arterial mineralization and atherosclerosis, such as PTX3, SPP1, LOX, etc., whereas vasodilation and physiological regulatory genes such as MGP, ACTA2, and MYL9 were conversely enriched in conventional IA-derived VSMCs." (PMID 35874788, 2022). "In addition, Spp1 is co-expressed with KnowTID_00005157, NONMMUT061712, and KnowTID_00003604, revealing a relationship between lncRNAs and atherosclerosis." (PMID 31446617, 2019). "In summary, our results support the conclusion that these proteins (i.e., SPP1, ATP6V0D2, CHI3L1, and BDNF) likely play important roles in the development of atherosclerosis-related diseases and further indicate that they are potential diagnostic and therapeutic biomarkers." (PMID 31682178, 2019). "Furthermore, our study indicates that SPP1, CD36, ATP6V0D2, CHI3L1, MYH11, and BDNF, which showed favorable diagnostic performance and high correlations with several clinical biochemical parameters, may potentially serve as biomarkers to diagnose and monitor the prognosis of atherosclerosis." (PMID 31682178, 2019).
pulmonary fibrosis (105 papers, 2008 to 2026). Chronic progressive interstitial lung disorder characterized by the replacement of the lung tissue by connective tissue, leading to progressive dyspnea, respiratory failure, or right heart failure. "Animal models demonstrated an increase in SPP1-expressing macrophages, associated with lung fibrosis, while blocking SPP1 reduced mortality and inflammation, indicating its potential as a therapeutic target." (PMID 40943770, 2025). "Osteopontin (OPN, SPP1) is a matrix protein significantly associated with pulmonary fibrosis and supports macrophage proliferation." (PMID 39632841, 2024). "Our data support that Spp1+ Mo-Macs, like Ly6G+ Macs, can also exert beneficial roles, while other Spp1+ Mo-Macs can become dysregulated, persistent and pathogenic, like in chronic Covid-19 or idiopathic pulmonary fibrosis." (PMID 39093958, 2024). "SPP1 contributes to human fibrotic lung disease, and increases in SPP1 are associated with pulmonary fibrosis and with the development of fibrosis in a number of animal models." (PMID 26955063, 2016). "Of note, the gene encoding OPN (Spp1) was recently shown as one of the most highly upregulated genes in type I collagen-producing lung myofibroblasts during bleomycin-induced lung fibrosis." (PMID 26859835, 2016). "SPP1 has been associated with lung fibrosis in systemic sclerosis." (PMID 39989459, 2025). "In this study, we hypothesized that differences in sensitivity to silica-induced pulmonary fibrosis between male and female mice are caused, in part, by alterations in the proinflammatory and profibrotic protein SPP1." (PMID 26955063, 2016). "Thus, this study examined whether altered SPP1 expression is associated with sex difference in silica-induced pulmonary fibrosis in mice." (PMID 26955063, 2016). "However, studies for COL3A1, which encodes for collagen 3A1, have shown that expression of this gene is positively regulated by SPP1 in a murine model of asbestos-induced lung fibrosis and that over-expression of the gene is linked to fibrosis and tissue remodeling." (PMID 25248511, 2014). "Earlier work also implicated SPP1 as a driver of fibrosis, in particular a study linking bleomycin-induced pulmonary fibrosis to SPP1-expressing alveolar macrophages." (PMID 39989459, 2025). "In a model of multi-walled carbon nanotube (MWCNT) exposure, SPP1 enhances lung fibrosis by upregulating TGF-β and stimulating myofibroblast differentiation in vivo." (PMID 40559389, 2025). "(i) SPP1 in idiopathic pulmonary fibrosis (IPF): ILD is an umbrella term for a group of disorders characterized by irreversible parenchymal fibrosis." (PMID 40559389, 2025). "Elevated serum and BAL fluid SPP1 levels can be a potential biomarker for ILDs, and the global knockout of SPP1 can protect animals from developing pulmonary fibrosis in various experimental models of pulmonary fibrosis." (PMID 40559389, 2025). "In vivo treatment with an SPP1 inhibitor enhances lung function and ameliorates idiopathic pulmonary fibrosis (IPF)." (PMID 41293726, 2025). "Research shows that SPP1 serves as a specific marker for a profibrotic macrophage subpopulation that expands dramatically in idiopathic pulmonary fibrosis (IPF)." (PMID 41293726, 2025). "FCN1, FABP4, and SPP1 macrophages are involved in the pathogenesis of lung fibrosis; SPP1 macrophages demonstrate upregulated expression in both SSc-ILD and IPF." (PMID 38937794, 2024). "SPP1+ macrophages have been identified previously as increased in fibrotic tissues and playing a role in the pulmonary fibrosis and resolution of inflammation." (PMID 38902328, 2024). "SPP1+ macrophages have previously been found in various tumor tissues, and SPP1 has a profibrotic role in skin and lung fibrosis." (PMID 39158018, 2024). "SPP1 (osteopontin) has been shown to promote fibroblast migration, adhesion, and survival, contributing to the development of pulmonary fibrosis." (PMID 39519222, 2024).
pulmonary fibrosis (continued). "A recent meta-analysis study showed that there was a higher increase in the expression level of SPP1 in patients with idiopathic pulmonary fibrosis (IPF)." (PMID 38919629, 2024). "For pulmonary fibrosis mice, compared to the control group, the expression of Spp1 in the model group was significantly increased (p < 0.05), consistent with the results of data analysis and HFL fibroblast cell qPCR experimentation." (PMID 37794454, 2023). "Independently, several recently published studies corroborated an SPP1+ macrophage subset in lung fibrosis." (PMID 36807143, 2023). "A recent study suggests that expression of Fcn1, Spp1, and Fabp4 is enhanced in monocyte-derived, pro-fibrotic, and normal alveolar macrophage populations of idiopathic pulmonary fibrosis." (PMID 35892659, 2022). "Regarding SPP1, macrophages expressing high levels of this marker have important effects on pulmonary fibrosis." (PMID 36685840, 2022). "Secretory phosphoprotein 1(SPP1) is a protein formerly related to pulmonary fibrosis and COPD in lung process in mice." (PMID 36507532, 2022). "This IM subtype seems to be consistent with previously reported SPP1/MERTK-expressing macrophages in idiopathic pulmonary fibrosis." (PMID 35820705, 2022). "Previous studies have found that the SPP1 gene is highly expressed in idiopathic pulmonary fibrosis (IPF), the occurrence, and metastasis of multiple tumors." (PMID 33816621, 2021). "Prior studies reported that low-level local proliferation of macrophages that highly express SPP1 in the normal lung tissue was strikingly increased in IPF lungs, and macrophages that highly express SPP1 importantly contribute to lung fibrosis in IPF34." (PMID 34476240, 2021). "Pulmonary myofibroblasts can be activated by highly proliferative SPP1 macrophages, in turn, contributing vitally to lung fibrosis." (PMID 34366885, 2021). "A recent paper with IPF shows that Spp1 is primarily expressed in myeloid cells in interstitial pulmonary fibrosis and IL-6 stimulates OPN expression in macrophages, which sensitizes and mobilizes fibroblasts toward other fibrogenic growth factors." (PMID 34830342, 2021). "Morse demonstrated that in idiopathic pulmonary fibrosis (IPF), macrophages highly expressing SPP1 contribute importantly to lung fibrosis." (PMID 32778054, 2020). "Genes involved in pulmonary fibrosis processes found to be upregulated in CIPF compared with healthy WHWTs in cluster M1 included FN1, SPP1, CXCL8, and PLAU (encoding plasminogen activator urokinase)." (PMID 33384697, 2020). "We identified four overexpressed genes associated with pulmonary fibrosis processes in CIPF compared with healthy dogs in this cluster including FN1, SPP1, CXCL8, and PLAU." (PMID 33384697, 2020). "Gene-targeted Spp1–/– mice developed less bleomycin-induced pulmonary fibrosis as well as reduced injury in models of renal, heart, kidney, and liver fibrosis." (PMID 26955063, 2016). "Lung SPP1 increases in humans with pulmonary fibrosis and in mouse and rat models of pulmonary fibrosis." (PMID 26955063, 2016). "To confirm the role of estrogen in determining SPP1 levels and silica-induced lung fibrosis, we pretreated male mice with estrogen for 21 days prior to silica administration." (PMID 26955063, 2016). "Secreted phosphoprotein 1 and sex-specific differences in silica-induced pulmonary fibrosis in mice." (PMID 26955063, 2016). "Notably, recent research in pulmonary fibrosis has revealed that inhibition of SPP1 can attenuate lung fibrosis, highlighting a potential therapeutic avenue for treating this condition." (PMID 40072075, 2025). "Specifically, in IPF patients, SPP1, which is highly expressed in alveolar epithelial cells, can induce the proliferation and migration of fibroblasts and epithelial cells, thereby accelerating the process of pulmonary fibrosis." (PMID 40149666, 2025).